CDC42 (cell division cycle 42)
Diseases named in the same sentence as CDC42 in open-access papers (continued):
Sharing a sentence is not in itself a finding about the gene and the disease.
glioma (continued). "Enhanced F‐actin assembly and elongation leading to increased filopodia formation and motility of GBM are clinically relevant phenotypes of the Cdc42‐mediated cytoskeletal signature activated by the novel CTRP8/RLN2‐RXFP1‐JAK3‐STAT3 cascade in human glioma." (PMID 33960104, 2022). "In glioma, Slit homolog protein/roundabout homolog 1 (Slit-Robo1) can reduce the activity of Cdc42 to inhibit the invasion of cancer cells." (PMID 35154449, 2022). "CTRP8 induced a marked shift from inactive to active GTP‐bound Cdc42 in human glioma cells, indicating a novel role of CTRP8 in regulating Cdc42 activity." (PMID 33960104, 2022). "While tofacitinib and S3I‐201 did not affect basic levels of Cdc42 protein, both inhibitors blocked the upregulation of Cdc42 in response to CTRP8 treatment in human glioma cells." (PMID 33960104, 2022). "Here, the downregulation of CDC42 and cytoskeletal protein F-actin was observed in 3D collagen/FN cultured glioma cells, whereas blockade of integrin αvβ3 reversed the phenomenon." (PMID 33408794, 2021). "Previous research reported that microRNA-384 inhibits proliferation, migration and invasion of glioma by targeting at CDC42." (PMID 33152231, 2021). "As expected, reduced NUPR1 and increased Nestin expression were observed in 3D collagen/FN cultured glioma cells, whereas blockade of integrin αvβ3 or CDC42 overexpression reversed the phenomenon." (PMID 33408794, 2021). "Together, these results suggested that the integrin αvβ3/CDC42/F-actin/YAP-1/NUPR1/Nestin signaling pathway was activated in 3D collagen/FN cultured glioma cells and induced glioma cell proliferation." (PMID 33408794, 2021). "We observed reduced nuclear but elevated cytoplasmic YAP-1 in the 3D collagen/FN-cultured glioma cells, whereas integrin αvβ3 suppression or CDC42 overexpression significantly increased the YAP-1 expression in the nucleus." (PMID 33408794, 2021). "Knockdown of IQGAP1 inhibits both Rac1- and Cdc42-mediated migration and invasion of glioma cells and leads to the suppression of several other components of the invasion process such as MMPs." (PMID 32089990, 2020). "Further, constitutively active Cdc42 reduced survival in a PDX model of glioma, while increasing the invasive capacity in sphere exit assays." (PMID 32102991, 2020). "Cathepsin L was found to be a strong promoter of X-ray-induced glioma cell invasion by regulating Cdc42-mediated cytoskeletal remodeling, a process which was abolished once Cathepsin L was knocked down and Cdc42 levels decreased." (PMID 32089990, 2020). "In general, increased HA expression is associated with an increase in motility and migration of glioma, probably via a CD44 or RHAMM induced activation of Rho GTPases, such as Rac1 or Cdc42." (PMID 31003495, 2019). "The mutual inhibition of RhoA and Rac1 is further complicated by Cdc42 being capable of activating Rac1 in glioma." (PMID 31003495, 2019). "Conversely, to investigate the role of Cdc42 overexpression in glioma cells, we generated stable glioma cell lines with doxycycline-inducible wild type (WT), constitutively active (CA), and dominant negative (DN) Cdc42." (PMID 27486972, 2016). "It is conceivable that these GEFs are involved in the regulation of oncogenic Cdc42 activity in glioma cells." (PMID 27486972, 2016). "In glioma and esophageal cancer, negative regulation of Slit2 on Cdc42 and cell migration also had been reported, suggesting Cdc42 a common key target of the Slit2-Robo1 signaling in human cancers." (PMID 27923383, 2016). "We show that activation of Cdc42 expression enhances the migration and invasion of human glioma cells in an orthotopic glioma model." (PMID 27486972, 2016). "By now, we found that knockdown of ARHGDIA by siRNA resulted in activating the GTPase activity of Cdc42, Rac1, RhoA, and pAkt to promote glioma cell proliferation and migration." (PMID 27726098, 2016).
glioma (continued). "Due to the important role of ARHGDIA in the regulation of Rho GTPase, then how does its decreased expression regulate its effector proteins including Rac1/cdc42 and RhoA in glioma cells?" (PMID 27726098, 2016). "Taken together, these results indicated that activated Cdc42 leads to a significant increase in glioma cell migration." (PMID 27486972, 2016). "Mass spectrometry of Cdc42 immunoprecipitates of glioma cell lysates revealed a number of putative binding partners." (PMID 27486972, 2016). "The Slit-Robo Rho GTPase activating protein 1 (srGAP1) is a key GTPase activating protein (GAP) downstream of Slit-Robo pathway, and has been shown to inhibit neuronal migration and glioma cell invasion by reducing the activation of Cdc42." (PMID 27923383, 2016). "Together, our analyses show that the protein level of ARHGDIA, which is known to be a negative regulator of Rho GTPases such as Rac1, Cdc42 and Rho, is decreased in glioma tumors compared with control brain tissues." (PMID 26761212, 2016). "Taken together, these results suggest that knockdown of Cdc42 reduces filopodia formation and actin stress fiber formation in glioma cells, and decreases their migratory and invasive phenotype, whereas there is little impact on cell viability." (PMID 27486972, 2016). "We generated stable doxycycline-inducible clones expressing wild type (WT)-, constitutively active (CA)-, and dominant negative (DN)-Cdc42 in three different human glioma cell lines." (PMID 27486972, 2016). "LRRC4/NGL-2 overexpression inhibited glioma cell growth and invasion through miR-185-mediated CDC42 and RhoA direct regulation and VEGFA indirect regulation." (PMID 25526788, 2014). "The activation of Rac1 in neurotensin neuropeptide treated glioma cells was described in parallel with Cdc42 activity, although the dependence of one GTPase on the other for activation was not explored." (PMID 24109588, 2013). "The TWEAK-Fn14 ligand receptor axis-induced activation of Rac1 is one mechanism to enhance Rac1-GTP that is dependent upon a functional and activated Cdc42 protein; the depletion of Cdc42 abrogated glioma cell migration in vitro and invasion ex vivo." (PMID 24109588, 2013). "By inhibiting the activation of Cdc42 showed the importance in reducing motility and invasion in glioma cells." (PMID 23677714, 2013). "The signaling between Slit2 and its binding partner, Robo 1, inhibits glioma cell migration in vitro and in vivo by inactivating CDC42-GTP, a Rho GTPase which induces the complexing of WASp and the Arp2/3 complex with actin to promote podosome formation." (PMID 23119100, 2012). "We found that TRIM56 expression was directly regulated by SP1, and TRIM56 enhanced glioma cell migration and invasion via activation of CDC42, which was mediated through the interaction of TRIM56 with IQGAP1 to increase the K48-K63-linked ubiquitination transition of IQGAP1." (PMID 36870986, 2023). "To explore whether TRIM56 promoted glioma cell motility by regulating CDC42 activation, we carried out Transwell chamber migration and invasion assays on glioma cells under TRIM56 overexpression and CDC42 knockdown conditions." (PMID 36870986, 2023). "This evidence suggests that CDC42 plays a role in the development of glioma." (PMID 37476838, 2023). "The expression of CDC42 in clinical features and biological functions of glioma was analyzed, including differential expression analysis, survival analysis, Gene Ontology (GO), Kyoto Encyclopedia of Genes and Genomes (KEGG) analysis, and immune infiltration analysis." (PMID 37476838, 2023). "The targeted inhibition of CDC42 expression has been shown to release the antineoplastic ability of effector T cells; therefore, more research into the mechanism and effectiveness of CDC42 in tumor evolution and extension is necessary for glioma-targeted therapy." (PMID 37476838, 2023).
glioma (continued). "In conclusion, our study provides insights into the mechanisms through which TRIM56 promotes glioma motility, i.e., by regulating IQGAP1 ubiquitination to promote CDC42 activation, which might be clinically targeted for the treatment of glioma." (PMID 36870986, 2023). "It was demonstrated that Slit2/ROBO1 signaling prevented glioma cell motility and invasion by inactivating Cdc42-GTP, even though the precise mechanisms behind this tumor-suppressive gene impact of Slit2/ROBO1 remain unknown." (PMID 38137332, 2023). "Our in vitro results demonstrated that 3D collagen/FN culture could induce the PI3K/AKT and CDC42/YAP/NUPR1 signal activation in glioma cells, resulting in growth factors SOX2/Nestin up-regulation." (PMID 33408794, 2021). "Recently, miRNA-29 family (miR-29a/b/c) was proven as proliferation, invasion and migration suppressors for gliomas by targeting cell division cycle 42 (CDC42) and Sterol regulatory element binding protein 1 (SREBP-1)/SREBP cleavage-activating protein (SCAP) in animal models." (PMID 34066132, 2021). "Findings regarding the role of Rac1 in glioma cell migration and invasion parallel those of Cdc42, for both, promote these two processes, bind to similar domains, are activated by common GEFs, and have the same intracellular location (at the front edge of the cell)." (PMID 32089990, 2020). "Additionally, invading glioma cells exhibit an increased Cdc42 and Rac1 activity, but a decreased activity of RhoA at the cell front, held responsible for the enhanced migration of leader cells." (PMID 31003495, 2019). "As expected, we found that Cdc42 co-localized with filopodia in glioma cells, and Cdc42 knockdown with siRNA decreased filopodia formation and induced a change in shape towards polygonal (A172 and U87MG), or more rounded (U118MG) morphologies, accompanied by a reduction in actin stress fibers." (PMID 27486972, 2016). "As a result, it is possible to consider that glioma invasion could also be significantly reduced through the inhibition of these Cdc42 GEFs." (PMID 27486972, 2016). "Therefore, the downregulation of ARHGDIA regulates GTPase activity of Cdc42, Rac1, and RhoA, subsequently, increases Akt phosphorylation and leads to glioma cell proliferation and migration." (PMID 27726098, 2016). "These molecular targets which bind to CA-Cdc42 may facilitate the indirect localization of activated Cdc42 in human glioma samples." (PMID 27486972, 2016). "This co-localization suggests that active Cdc42 may regulate pFAK distribution enhancing glioma migration and invasiveness." (PMID 27486972, 2016). "The Rho family GEFs, VAV3 and Trio, regulate the invasive phenotype of glioma cells, and a recent study identified the two GEFs, Ect2 and Trio, as activators of various Rho GTPases including cdc42 and Rac1 downstream of Tweak and as regulators of cell migration." (PMID 25682201, 2015). "Cdc42 activation has also been demonstrated alongside Rac1 activation in GB cells downstream of PDGFRα association with SHP-2 non-receptor protein tyrosine phosphatase and Dynamin 2 (Dyn2) to promote glioma cell migration." (PMID 24109588, 2013). "All evidence suggested that CDC42 may be a potential target for glioma immunotherapy." (PMID 37476838, 2023). "All evidence suggests that CDC42 may be a target for glioma immunotherapy." (PMID 37476838, 2023). "It suggested KIF4A may regulate glioma cells growth and mobility through the Rac1/Cdc42 pathway." (PMID 36606197, 2022). "We, therefore, questioned whether CDC42 could partly mediate miR-10b effects on glioma growth." (PMID 35033060, 2022). "Therefore, SNHG15 and its target miR-153 could serve as new potential therapeutic targets for the antiangiogenic treatment of glioma through the downregulation of CDC42." (PMID 34771549, 2021). "Moreover, it was reported that miR-29, as an invasion suppressor, downregulates CDC42 in gliomas." (PMID 34771549, 2021).
glioma (continued). "An increase in R (-)-2-hydroxyglutarate in gliomas harboring IDH mutations has been found to prevent the association of MLK3 with Cdc42 and further inhibit the activity of MLK3, which may be one of the reasons for the better prognosis in patients with IDH-mut gliomas." (PMID 33692940, 2020). "Finally, we examined glioma cell viability after Cdc42 specific siRNA knockdown." (PMID 27486972, 2016). "Second, Cdc42 also controls the focal development of matrix-degrading structures called podosomes, found in normal cell types, such as macrophages and smooth muscle cells, and of functionally similar structures called invadopodia in several metastatic tumors including glioma." (PMID 25032689, 2014). "Furthermore, CDC42 and RhoA were inversely correlated with miR-185 expression in gliomas." (PMID 25526788, 2014). "RhoG can also activate Rac1 and Cdc42 in the regulation of neuronal process plasticity, thus it remains a possibility that deregulated neuronal signaling and development pathways may also utilize RhoG to promote glioma malignancy." (PMID 24109588, 2013). "In the glioma mechanism, NSUN4-mediated m5C changes regulate ALYREF binding to CDC42 mRNA, affecting CDC42 mRNA stability." (PMID 41462962, 2025). "CDC42 knockdown or treatment with the CDC42 specific inhibitor ZCL278 reversed the enhanced migration and invasion abilities of glioma cells under TRIM56 overexpression in U87, U251 and LN229 cells." (PMID 36870986, 2023). "Considering that the differentially expressed genes regulated by TRIM56 knockdown were highly enriched in the Rho GTPase signaling and the motility-promoting effect of TRIM56 on glioma cells, we further assessed the effect of TRIM56 on CDC42 activation." (PMID 36870986, 2023). "We provided evidence that collagen/FN complex regulates glioma stemness via an integrin αvβ3-activated PI3K/AKT/SOX2 and CDC42/F-actin/YAP-1/Nupr1/Nestin signaling network." (PMID 33408794, 2021). "Our study provided evidence suggesting that collagen and FN collaborate to facilitate proliferation and tumorigenesis of glioma cells through the PI3K/AKT/SOX2 and CDC42/F-actin/YAP-1/Nupr1/Nestin pro-survival signaling networks." (PMID 33408794, 2021). "We identified the integrin αvβ3/CDC42/F-actin/YAP-1/Nupr1/Nestin signaling pathway, which was independent of the PI3K/AKT signaling in 3D collagen/FN cultured glioma cells." (PMID 33408794, 2021). "A significant decrease in Cdc42 expression was demonstrated by western blot analysis in A172, U87MG and U118MG human glioma cells at 72 hrs post-transfection." (PMID 27486972, 2016). "According to another study, PI3K/Cdc42 and PI3K/Rac1 pathways are important in LPA-mediated migration of glioma cells." (PMID 21943101, 2011). "CDC42 transitions between an active (GTP-bound) and an inactive (GDP-bound) state, where the former coordinates cytoskeletal processes and promotes invadopodium formation to support tumor cell invasion and dissemination, including that of glioma cells." (PMID 36870986, 2023). "To precisely unravel the pathways that were related to the function of KIF4A in cytoskeletal remodeling of glioma, we hypnosis that whether KIF4A regulated F-actin through RhoA or Rac1/Cdc42." (PMID 36606197, 2022). "More importantly, we identified that collagen/FN stimulated glioma progression through integrin αvβ3-induced PI3K/AKT/SOX2 and CDC42/F-actin/YAP-1/Nupr1/Nestin double signal activation simultaneously, expounding the underlying mechanism of the extracellular matrix-induced tumor signaling network." (PMID 33408794, 2021). "The results showed that CCND1, CDC42, RAF1, and CHEK1 were highly expressed in gliomas." (PMID 33676540, 2021). "In addition, p38, MAPK, phosphatidylinositol 3-kinase (PI3K), Rac1, Cdc42, and JNK-dependent pathways are important factors for lysophosphatidic acid (LPA) signaling, which is related to glioma cell migration." (PMID 30373180, 2018).
glioma (continued). "The OrisTM Cell Migration Assay was used to determine the distance glioma cells migrated at 24 hrs when cell number or viability is not altered by Cdc42 expression levels." (PMID 27486972, 2016). "Likewise, small nucleolar RNA host gene 15 (SNHG15) lncRNA knockdown reduced the expression levels of pro-angiogenic factor cell division control protein 42 homolog (CDC42) and VEGF because the miR-153 was longer sponged and led to suppression of tumor angiogenesis in adult glioma cells." (PMID 37444408, 2023). "In addition, we explored the CGGA, an independent glioma database, and validated expressions of the CCNB1/CDC42/MAPK7/CD44 gene signatures in WHO grade II, III, and IV GBM tumors using the Analysis of variance (ANOVA), with p < 0.05 considered statistically significant." (PMID 35008426, 2022). "In addition, previous studies proved that δ-catenin has an influence in other small GTPases, such as Cdc42 and RhoA, which was not investigated in glioma cell lines." (PMID 22151302, 2011).